IGHV3-74 (immunoglobulin heavy variable 3-74)
Description:
V region of the variable domain of immunoglobulin heavy chains that participates in the antigen recognition. Immunoglobulins, also known as antibodies, are membrane-bound or secreted glycoproteins produced by B lymphocytes. In the recognition phase of humoral immunity, the membrane-bound immunoglobulins serve as receptors which, upon binding of a specific antigen, trigger the clonal expansion and differentiation of B lymphocytes into immunoglobulins-secreting plasma cells. Secreted immunoglobulins mediate the effector phase of humoral immunity, which results in the elimination of bound antigens. The antigen binding site is formed by the variable domain of one heavy chain, together with that of its associated light chain. Thus, each immunoglobulin has two antigen binding sites with remarkable affinity for a particular antigen. The variable domains are assembled by a process called V-(D)-J rearrangement and can then be subjected to somatic hypermutations which, after exposure to antigen and selection, allow affinity maturation for a particular antigen.
Synonyms: IGHV374; VH
Gene: Immunoglobulin variable (V) gene on chromosome 14 (106,810,442 to 106,811,131, reverse strand). Ensembl gene ENSG00000224650.
Subcellular location: Secreted; Cell membrane
Gene Ontology:
Molecular function: antigen binding
Biological process: immunoglobulin mediated immune response
Cellular component: extracellular region; plasma membrane
Homologues: Paralogues in human: IGHV3OR16-13 (97% identical), IGHV3-23 (90% identical), IGHV3-48 (89% identical), IGHV3-64 (89% identical), IGHV3-7 (89% identical), IGHV3-66 (88% identical), IGHV3-21 (87% identical), IGHV3-33 (87% identical), IGHV3OR16-10 (87% identical), IGHV3-11 (86% identical), IGHV3-20 (86% identical), IGHV3-30 (86% identical), and 65 more.